DVL3 (dishevelled segment polarity protein 3)
Diseases named in the same sentence as DVL3 in open-access papers (continued):
Sharing a sentence is not in itself a finding about the gene and the disease.
tumor (continued). "According to human data derived from the TCGA and GTEx databases, decreased expressions of miR-4516 and increased expressions of Wnt 8B, DVL3, FOSL1, CCNA1, CCNB1, CDK1, and CDK2 in tumor tissue contributed to the progression of LUAD." (PMID 38930863, 2024). "We found that the expression of NPHP3, DVL1, and DVL3 was significantly higher and the expression of ANKS6 was significantly lower in the primary tumor in comparison to the normal solid tissue." (PMID 39596188, 2024). "The expression of DVL3 was positively related and the expression of ANKS6 was negatively related to the tumor’s histological grade." (PMID 39596188, 2024). "Our study identified that DVL3, one of DVL family members, was overexpressed in primary tumor tissue and multiple cell lines of CRC." (PMID 37147666, 2023). "MEX3A is upregulated in EC and promotes tumor progression by activating EMT and regulating the Wnt/β-catenin pathway via DVL3." (PMID 36614043, 2022). "In this tumor type, RAC1B can enhance Dishevelled-3 (DVL3)-mediated Wnt pathway signaling and induction of Wnt target genes specifically involved in decreasing the adhesive properties of CRC cells." (PMID 30621237, 2019). "The amplification of PIK3CA, PTEN, KRAS, SOX2, DVL3, and TP63 were present in all tumor samples in M7 and M9, including N4 in M7." (PMID 29050228, 2017). "This study compared the expression levels of miR-4516, Wnt 8B, FZD2, DVL3, FOSL1, CDK1, CDK2, CCNA1, and CCNB1 in primary LUAD tumor tissue with those in normal lung tissue using data from The Cancer Genome Atlas (TCGA) database to assess the consistency of our findings with the human sample." (PMID 38930863, 2024). "We assessed the correlation of INVS and genes of interest in its interactome (NPHP3, DVL1, DVL3, and ANKS6) with tumor immune infiltration and expression using different algorithms (XCELL, TIMER, QUANTISEQ, EPIC, CIBERSORT, CIBERSORT-ABS, and MCPCOUNTER) by using GEPIA." (PMID 39596188, 2024). "Normal lung tissue samples were mostly negative or weakly positive for DVL3, while tumor tissue samples were positive or strongly positive." (PMID 37859822, 2023). "DVL3 expression was also higher in CRC tissues with lymph node metastasis than tumor tissues without metastasis, and correlated with poor prognosis of CRC patients." (PMID 37147666, 2023). "DVL3 belongs to the DVL family, which is the cytoplasmic mediator of the Wnt/b-catenin signaling pathway and plays an important role in embryonic development, cell differentiation, and tumor formation." (PMID 35273597, 2022). "Both the DVL3 and the TRAMP C1 tumours were positive for NKX3.1 throughout the tumour section." (PMID 33003551, 2020). "By enhancing DVL3-mediated Wnt pathway signaling and induction of Wnt target genes involved in decreasing adhesion of CRC cells, RAC1B overexpression may facilitate tumor progression." (PMID 30621237, 2019). "Worth to note, CNAs of 37 genes were exclusively found in G3 tumours such as WNT7B (4 gains), BAD (3 gains), WEGFB (3 gains) and HDAC2 (3 losses) in respect to 65 CNA genes exclusively presented in G1 tumours, such as GRB2 (5 losses) and FGF21, STAT3, CTNNA3 and DVL3 with 3 losses each." (PMID 28486536, 2017). "Western analysis carried out on tumor lysates revealed that sFRP1 was present in tumors arising from MDA-MB-231/sFRP1-P1 cells and WNT signaling was downregulated, since there was a decrease in the amount of p-DVL3 in comparison with control tumors." (PMID 19473496, 2009). "Therefore, it could be possible that DVL1 and DVL3 are only targeted by miR-1247-5p specifically in the adrenal of CPA and PBMAH patients, leading to its characterized tumor progression." (PMID 35887024, 2022). "Not a single tumor showed only nuclear localization of the DVL3 protein." (PMID 29200599, 2017).
adenocarcinoma (3 papers, 2012 to 2023). A common cancer characterized by the presence of malignant glandular cells. "In the present study, the expression frequencies of DVL-3 mRNA and δ-catenin mRNA were significantly greater in the adenocarcinoma group (P < 0.01) compared with the benign lung disease group." (PMID 22461838, 2012). "Both DVL-3 mRNA and δ-catenin mRNA were significantly more likely to be expressed in malignant than in benign lung disease (P < 0.01), and the expressions of DVL-3 mRNA and δ-catenin mRNA were more likely to be positive than cytology in adenocarcinoma (P < 0.01)." (PMID 22461838, 2012).
infection (1 paper, 2010). The state of being infected such as from the introduction of a foreign agent such as serum, vaccine, antigenic substance or organism. "According to this, we found reduced levels of pLRP6 in NCI-N87 cells deficient for Dvl2 and Dvl3 after infection with H. pylori." (PMID 20137080, 2010). "To study whether nuclear translocation of β-catenin in H. pylori-infected epithelial NCI-N87 cells depends on LRP6, Dvl2 or Dvl3, we performed an infection of stable knockdown cell lines deficient for LRP6, Dvl2 or Dvl3." (PMID 20137080, 2010).
DVL3 also shares sentences with these, for which no sentence is quoted: non-small cell lung carcinoma (3 papers); lung adenocarcinoma (2); metastatic prostate carcinoma (2); spina bifida (2); Alzheimer disease (1); anaplastic astrocytoma (1); aortic stenosis (1); asthenia (1); atrial fibrillation (1); brain tumors (1); Carpenter syndrome (1); depression (1); embryonic carcinoma (1); endometrial carcinoma (1); Gardner syndrome (1); gastric cancer (1); generalized epilepsy (1); hearing loss (1); Hirschsprung disease (1); interstitial cystitis (1); liver cancer (1); lymph node metastasis (1); malignant pleural mesothelioma (1); mantle cell lymphoma (1); meningioma (1); metabolic disorders (1); Multiple Myeloma (1); neurological diseases (1); Obesity (1); orofaciodigital syndrome IV (1).
A further 10 diseases each share a sentence with DVL3 in 1 paper.